GRAMD1C (GRAM domain containing 1C)
Description:
Cholesterol transporter that mediates non-vesicular transport of cholesterol from the plasma membrane (PM) to the endoplasmic reticulum (ER) (By similarity). Contains unique domains for binding cholesterol and the PM, thereby serving as a molecular bridge for the transfer of cholesterol from the PM to the ER (By similarity). Plays a crucial role in cholesterol homeostasis and has the unique ability to localize to the PM based on the level of membrane cholesterol (By similarity). In lipid-poor conditions localizes to the ER membrane and in response to excess cholesterol in the PM is recruited to the endoplasmic reticulum-plasma membrane contact sites (EPCS) which is mediated by the GRAM domain (By similarity). At the EPCS, the sterol-binding VASt/ASTER domain binds to the cholesterol in the PM and facilitates its transfer from the PM to ER (By similarity).
Synonyms: LAMc; DKFZp434C0328
Tractability: Antibody: UniProt places it where antibodies can reach, with medium confidence; UniProt predicts a signal peptide or a membrane-spanning region; its Gene Ontology location is reachable by antibodies, with medium confidence. PROTAC: ubiquitination databases record sites on it.
Gene: Protein-coding gene on chromosome 3 (113,828,182 to 113,947,179, forward strand). Ensembl gene ENSG00000178075.
Subcellular location: Endoplasmic reticulum membrane; Cell membrane
Subcellular location (Human Protein Atlas): Cytosol; Plasma membrane
Gene Ontology:
Molecular function: protein binding; cholesterol binding; cholesterol transfer activity
Biological process: intracellular cholesterol transport; intracellular sterol transport
Cellular component: endoplasmic reticulum membrane; endoplasmic reticulum-plasma membrane contact site; plasma membrane; organelle membrane contact site
Genetic constraint (gnomAD): Loss-of-function variants: 2 observed, 1.94 expected, observed/expected ratio (o/e) 1.03, 90% interval 0.37 to 1.88. That is too few expected variants to judge how well the gene tolerates losing a copy. Missense variants: 22 observed, 24.09 expected, observed/expected ratio (o/e) 0.91, 90% interval 0.65 to 1.3. Synonymous variants: 5 observed, 9.11 expected, observed/expected ratio (o/e) 0.55, 90% interval 0.29 to 1.15.
Homologues: Orthologues: chimpanzee GRAMD1C (99% identical), macaque GRAMD1C (97% identical), dog GRAMD1C (88% identical), rabbit GRAMD1C (87% identical), pig GRAMD1C (85% identical), rat Gramd1c (83% identical), mouse Gramd1c (82% identical), guinea pig GRAMD1C (56% identical), tropical clawed frog gramd1c (53% identical), zebrafish gramd1c (43% identical), Drosophila melanogaster GramD1B (32% identical), Caenorhabditis elegans ZC328.3 (24% identical). Paralogues in human: GRAMD1B (42% identical), GRAMD1A (38% identical), GRAMD2B (14% identical), GRAMD2A (10% identical).
Diseases named in the same sentence as GRAMD1C in open-access papers:
GRAMD1C is named in the same sentence as 15 diseases in open-access papers, as found by Europe PMC text mining. Sharing a sentence is not in itself a finding about the gene and the disease. The quoted sentences say what the papers report.
clear cell renal carcinoma (2 papers, 2022). A malignant epithelial neoplasm of the kidney characterized by the presence of lipid-containing clear cells within a vascular network. "Previously, a study reported that the downregulation of GRAMD1C could be a promising predictor of poor prognosis in renal clear cell carcinoma." (PMID 35999846, 2022).
liver disease (1 paper, 2024). "Given recent reports showing that Gramd1c is a direct transcriptional target of the bile acid sensing nuclear receptor FXR, additional studies are needed to further understand whether Aster-C-driven modulation of bile acid homeostasis may hold therapeutic potential in liver disease." (PMID 38694206, 2024).
tumor (5 papers, 2019 to 2026). "The most interesting thing we found about this study is the regulation of GRAMD1C on tumor-infiltrating immune cells, especially the regulatory T cells (Tregs)." (PMID 31875150, 2019). "Our study indicated that reduced GRAMD1C expression correlates with diverse clinical characteristics (gender, age, histologic grade, clinical stage, tumor status and distant metastasis)." (PMID 31875150, 2019). "In addition, based on clinical information acquired from TCGA and CIBERSORT results, we found that several tumor-infiltrating immune cells related to GRAMD1C expression have significant correlation with prognosis of KIRC patients, which is consistent with previous studies." (PMID 31875150, 2019). "Among these five prognosis-related genes, we found that INHBA and CD24 were oncogenic genes, while GRAMD1C, NFKBIA and ACSS2 were tumour suppressor genes." (PMID 35999846, 2022). "As overall survival is also affected by invasive and migration capabilities of the tumor, we analyzed migration of 786-O cells depleted of GRAMD1A, GRAMD1B and GRAMD1C using a wound-healing assay." (PMID 36270994, 2022). "The expression of GRAMD1C, NFKBIA, and ACSS2 was significantly higher in normal tissues than in tumour tissues (P < 0.001, P = 0.0096, and P < 0.001, respectively), which indicated that CD24 and INHBA were risk genes and that GRAMD1C, NFKBIA, and ACSS2 were protective genes." (PMID 35999846, 2022). "To further investigate the functions of GRAMD1C in KIRC, we performed immune-related analysis using CIBERSORT, which showed that the GRAMD1C expression significantly effects the leukocyte fraction in tumor microenvirenment of KIRC." (PMID 31875150, 2019). "Furthermore, while GRAMD1C expression was decreased in advanced-stage tumors, the expression of GRAMD1A and GRAMD1B showed an opposite pattern, with increased expression in late-stage tumor samples compared to early-stage tumor samples." (PMID 36270994, 2022).
cancer (2 papers, 2019 to 2022). A tumor composed of atypical neoplastic, often pleomorphic cells that invade other tissues. "Another important aspect of this study was that GRAMD1C expression was correlated with diverse well-known pathways associated with cancer processes and immune responses, such as mTOR signaling pathway, WNT signaling pathway and AKT pathway." (PMID 31875150, 2019). "GRAMD1C (GRAM Domain Containing 1C) has not been reported to relate to prognosis and immunotherapy in any cancers." (PMID 31875150, 2019). "GRAMD1C is a messenger RNA which has not been reported to relate to prognosis and respond to immunotherapy in any cancers." (PMID 31875150, 2019).
GRAMD1C also shares sentences with these, for which no sentence is quoted: laminopathies (3 papers); muscular dystrophy (3); Alexander disease (1); Arrhythmia (1); breast carcinoma (1); esophageal squamous cell carcinoma (1); Infertility (1); ovarian tumor (1); Progeria (1); renal carcinoma (1); tubulointerstitial nephritis (1).